DOCK8 (dedicator of cytokinesis 8)
Diseases named in the same sentence as DOCK8 in open-access papers (continued):
Sharing a sentence is not in itself a finding about the gene and the disease.
Bardet-Biedl syndrome (1 paper, 2018). A ciliopathy with multisystem involvement. "We applied our method in six use cases: phenotypes associated with the Rett, Lowe, Silver Russell, Bardet-Biedl syndromes, DOCK8 deficiency and Activated PI3-kinase Delta Syndrome (APDS)." (PMID 29855327, 2018). "We illustrate our approach on six rare diseases: DOCK8 deficiency, the Activated PI3-kinase Delta Syndrome (APDS), Rett, Lowe, Silver Russell and Bardet Biedl syndromes." (PMID 29855327, 2018).
blepharoconjunctivitis (1 paper, 2017). Inflammation of both the eyelids and the conjunctiva. "A similar case was reported in the literature of a tumorous HSV blepharoconjunctivitis in a patient with a DOCK8 deficiency." (PMID 29158737, 2017).
central nervous system vasculitis (1 paper, 2011). Vasculitis affecting the blood vessels of the brain and/or spinal cord. "DOCK8-HIES is also associated with susceptibility to Salmonella and Giardia infections as well as development of early onset malignancies and central nervous system vasculitis." (PMID 22126402, 2011).
combined immunodeficiency syndrome (1 paper, 2021). A combined immunodeficiency in which other clinical features are present in other organ systems in addition to immunodeficiency. "Defects in DOCK8 are known to lead to severe combined immunodeficiency syndromes, with morphological, developmental, and functional abnormalities of T- and B-cells." (PMID 35386989, 2021).
Cri-du-chat syndrome (1 paper, 2021). Monosomy 5p, also known as Cri du chat syndrome, is a rare autosomal deletion syndrome characterized by a mewing cry (cri du chat) in infancy, multiple congenital anomalies, intellectual disability, microcephaly, and facial dysmorphism. "For fetus 20, SNP array analysis revealed a 32 Mb deletion at 5p15.33p13.3 (involving CTNND2 and DOCK8) which caused cri-du-chat syndrome, and a 21 Mb duplication at 9p24.3p21.3 (involving KANK1) leading to 9p duplication syndrome." (PMID 33674646, 2021).
eczema herpeticum (1 paper, 2024). "Additionally, we could find one recent case report on dupilumab and DOCK8 deficiency with high IgE levels in a 6-year-old girl resulting in a successful remission of disseminated eczema herpeticum." (PMID 39936153, 2024).
experimental autoimmune encephalomyelitis (1 paper, 2020). An autoimmune demyelinating disease of the central nervous system that is produced experimentally in animals by the injection of homogenized brain or spinal cord in Freund's adjuvant. "It was recently reported that LRCH1 competes with Cdc42 for interaction with DOCK8 and restrains T cell migration in experimental autoimmune encephalomyelitis." (PMID 32631435, 2020). "A recent study indicates that LRCH1 act to restrain PKCα-DOCK8-Cdc42 module-mediated T cell migration in experimental autoimmune encephalomyelitis, through competing with Cdc42 for interaction with DOCK8." (PMID 32631435, 2020).
Familial hemophagocytic lymphohistiocytosis (1 paper, 2023). Familial Hemophagocytic lymphohistiocytosis (FHL) is a rare primary immunodeficiency characterized by a macrophage activation syndrome (see this term) with an onset usually occurring within a few months or less common several years after birth. "Additionally, and in agreement with a previous report, we also detected rare heterozygous mutations in some genes, including AP3B1, PRF1, LYST and DOCK8, that are associated with familial hemophagocytic lymphohistiocytosis in patients with MIS-C." (PMID 36282598, 2023).
gastric adenocarcinoma (1 paper, 2016). "Thus, PTPRD and DOCK8 deserve more scrutiny as potential TSGs in gastric adenocarcinoma." (PMID 26205786, 2016).
graft versus host disease (1 paper, 2022). An immune system disorder that occurs after allogeneic hematopoietic stem cell transplant and is a reaction of donor immune cells against host tissues. "One of the earliest manifestations of graft versus host disease (GVHD) in one of the transplanted DOCK8 patients was regression in the DOCK8 protein expression level which became normal again with improvement of GVHD." (PMID 35655284, 2022).
herpesvirus infections (1 paper, 2025). "The detection of HSV-1 reinforces the well-documented susceptibility of DOCK8-deficient individuals to persistent herpesvirus infections, likely due to impaired T-cell memory and cytotoxic responses." (PMID 40150657, 2025).
Hyperkeratosis (1 paper, 2017). Hyperkeratosis is a histopathological term defining a thickened stratum corneum and may be present in many different skin conditions, with many possible overlaps. "Histological and immunohistochemical analyses of the skin from Dock8−/− AND Tg mice revealed acanthosis, hyperkeratosis and mild spongiosis with massive infiltration of CD4+ T cells and, to lesser extent, eosinophils." (PMID 28067314, 2017).
ischemia (1 paper, 2016). A hypoperfusion of the BLOOD through an organ or tissue caused by a PATHOLOGIC CONSTRICTION or obstruction of its BLOOD VESSELS, or an absence of BLOOD CIRCULATION. "DOCK8-deficient patients reportedly develop moyamoya, which is considered a consequence of ischemia." (PMID 27113444, 2016).
Kostmann syndrome (1 paper, 2025). "Porphyromonas gingivalis was found in those with DOCK8 deficiency, while Prevotella intermedia was prevalent in Kostmann syndrome." (PMID 40150657, 2025).
liver disease (1 paper, 2021). "In case of abnormal liver function tests results, Cryptosporidium should be always ruled out in DOCK8-deficient patients, as it is a under-recognized cause of liver disease." (PMID 33936120, 2021).
lung adenocarcinoma (1 paper, 2016). A carcinoma that arises from the lung and is characterized by the presence of malignant glandular epithelial cells. "Furthermore, RSPO3, ADAMTS8 and DOCK8 were also related to the overall survival and disease-free survival of lung adenocarcinoma patients in the TCGA data." (PMID 27980454, 2016). "In addition, RSPO3, ADAMTS8 and DOCK8 were related to overall survival and disease-free survival (all P < 0.05) of lung adenocarcinoma patients in TCGA." (PMID 27980454, 2016). "During the process of researching the relationship between these 4 de-regulated genes and 3 pathways, we found that DOCK8 and the TGF-beta signaling pathway played significant roles in the metastasis of lung adenocarcinoma." (PMID 27980454, 2016). "Additionally, ADAMTS8, DMBT1 and DOCK8 were down-regulated in adenocarcinoma and STMN2 and TUSC3 were up-regulated in lung adenocarcinoma (all P < 0.01)." (PMID 27980454, 2016).
lymph node metastasis (1 paper, 2016). "DOCK8 was significantly more highly expressed in the advanced stages (III and IV, t = 3.482, P = 0.001) and cases with lymph node metastasis (t = 2.087, P = 0.037)." (PMID 27980454, 2016).
lymphoproliferative disorders (1 paper, 2025). "Although EBV and CMV were not investigated, DOCK8 deficiency has been associated with EBV-driven lymphoproliferative disorders and CMV-related opportunistic infections, suggesting that these viruses may still be present at undetectable levels or may emerge in later stages of disease progression." (PMID 40150657, 2025).
Macrocephaly (1 paper, 2021). Occipitofrontal (head) circumference greater than 97th centile compared to appropriate, age matched, sex-matched normal standards. "Here we report findings of duplications of chromosome location 9p24.3 (i.e., the DOCK8/KANK1 genes) in three unrelated patients, which provide evidence of the pathogenic impact of this duplication in patients with ID/DD, ASD, ADHD, and macrocephaly." (PMID 33455084, 2021). "In this study, only patient 2 had macrocephaly and his duplication overlapped the DOCK8 and KANK1 genes, unlike the remaining patients who carried an intragenic duplication of DOCK8 only." (PMID 33455084, 2021). "Additionally, mosaic duplication involving the DOCK8, DMRT1, DMRT2, DMRT3, and KANK1 genes were observed in patient 2, which may explain the presence of macrocephaly in this patient." (PMID 33455084, 2021). "Only five cases of intragenic duplication of DOCK8 were described in the DECIPHER v9.21 database, and these patients’ phenotypes included ID/DD (3/5, 60.00%), ASD (1/5, 20.00%), and no macrocephaly, microcephaly or ADHD (DECIPHER v9.21)." (PMID 33455084, 2021).
mental disorder (1 paper, 2018). A disease that has its basis in the disruption of mental process. "There is increasing evidence in the literature of the importance of DOCK8 for proper neurological functioning and its influence on some mental disorders and behavioural abnormalities." (PMID 29930340, 2018). "Hence, our study suggests that CNVs disrupting the DOCK8 gene, regardless of whether they are deletions or duplications, have a clinical relevance and are associated with a variety of mental disorders/abnormalities." (PMID 29930340, 2018).
non-Hodgkin lymphoma (1 paper, 2019). Distinct from Hodgkin lymphoma both morphologically and biologically, non-Hodgkin lymphoma (NHL) is characterized by the absence of Reed-Sternberg cells, can occur at any age, and usually presents as a localized or generalized lymphadenopathy associated with fever and weight loss. "The purpose of this paper is to report a case of DOCK8 deficiency in an Iraqi girl who had been clinically diagnosed as having HIES, with suspicion of non-Hodgkin lymphoma (NHL), in Iraq." (PMID 31242861, 2019).
Parkinson’s (1 paper, 2024). "CD4+ genes inversely associated with the PRS for Parkinson’s included DOCK8 and CD59." (PMID 38590520, 2024).
periodontal disease (1 paper, 2025). "In the context of DOCK8 deficiency, the elevated IgE levels could thus represent a further element reinforcing the systemic condition and periodontal disease link." (PMID 40871317, 2025). "Interestingly, in DOCK8 deficiency, the atopic profile, reflected by high IgE levels and eosinophilia, may further represent a mechanistic bridge linking systemic and periodontal disease." (PMID 40871317, 2025).
sickle cell disease (1 paper, 2024). Sickle cell anemias are chronic hemolytic diseases that may induce three types of acute accidents: severe anemia, severe bacterial infections, and ischemic vasoocclusive accidents (VOA) caused by sickle-shaped red blood cells obstructing small blood vessels and capillaries. "Benign indications for HSCT include sickle cell disease and genetic mutations leading to immunodeficiency diseases, i.e. GATA2, STAT3, DOCK8, PI3K gene mutations." (PMID 38756303, 2024).
systemic lupus erythematosus (1 paper, 2021). An autoimmune multi-organ disease typically associated with vasculopathy and autoantibody production. "Here, we report a patient with DOCK8 deficiency that was initially presented as systemic lupus erythematosus (SLE) without recurrent infections and treated with hematopoietic stem cell transplantation (HSCT)." (PMID 33787566, 2021).
thymoma (1 paper, 2021). A neoplasm arising from the epithelial cells of the thymus. "Specifically, BW5147α−β− mouse thymoma cell line that lacks endogenous expression of DOCK8 was stably transfected to express HA-tagged DOCK8, and used as an input." (PMID 33574036, 2021).
cancer (26 papers, 2014 to 2025). A tumor composed of atypical neoplastic, often pleomorphic cells that invade other tissues. "The result from a follow-up study of 136 patients with DOCK8 deficiency showed that 23 patients (17%) were diagnosed with malignant tumors, including 11 cases of hematological cancer, 9 cases of epithelial cancer and 5 cases of other malignant tumors." (PMID 36386145, 2022). "In particular, accumulating evidences showed the high correlation between DOCK8 mutations or deletions and cancer development." (PMID 36386145, 2022). "Progressive T-cell lymphoma and other cancers unrelated with viral infections have also been reported in DOCK8-deficienct patients." (PMID 36140582, 2022). "Severe allergic symptoms, skin viral infections, and malignancies are more specific for DOCK8-deficient patients." (PMID 36140582, 2022). "DOCK8 deficiency manifests with a variety of symptoms, including the development of severe viral infections of the skin like warts and molluscum, as well as a heightened susceptibility to cancer at a younger age." (PMID 38978914, 2024). "Here, we reviewed the common role of DOCK8 in immunity and tumorigenesis, which will help to understand the molecular mechanism of DOCK8 deficiency in cancer development and provide new option for the development of novel therapeutic strategy based on the genetic status of DOCK8." (PMID 36386145, 2022). "DOCK8 deficiency status characterizes by recurrent infections, atopy, and risk of cancer." (PMID 31242861, 2019). "Generally, mutations or deletions of DOCK8 may provide susceptibility to cancer." (PMID 36386145, 2022). "Among some genes associated with disease and immunity, DOK2 and TIMM17A are related to cancer, LMODI is linked to hypoperistalsis, MAVS is essential for virus-activated signaling pathways, and DOCK8 is linked to humoral immunity." (PMID 36139261, 2022). "This region also contains two other genes, PTPRD and DOCK8, that have been proposed as TSGs in other cancers." (PMID 26205786, 2016). "Similarly, its cytoskeletal role via MST1/DOCK8/WASP expands upon HMGB1’s known capacity to modulate cell migration in cancer and endothelial cells." (PMID 40985892, 2025). "In humans, DOCK8 deficiency leads to combined immunodeficiency disease (CID), which is clinically associated with chronic infection of a variety of microbial pathogens and is conducive to the development of malignant tumours." (PMID 36851274, 2023). "Here, we summarized and discussed the crucial roles of DOCK8 in various cancers." (PMID 36386145, 2022). "We also found that Annexin A2 suppressed DOCK8 expression, indicating that DOCK8 may be involved in Annexin A2-regulated cancer migration and progression." (PMID 26716413, 2016). "Therefore, we explored the attributes of eRNA target genes in relation to cancer genomic events and found that these genes, such as dedicator of cytokinesis 8 (DOCK8) and excision repair 6 (ERCC6), exhibit a high burden of mutations and amplifications or deletions change." (PMID 38863031, 2024). "The lack of wild-type transcript expression in benign and cancer cells implies that mutation may play a role in DOCK8 expression." (PMID 38206124, 2024). "However, whether overexpression of DOCK8 in tumors can increase the level of tumor immune infiltration is universal in various cancers warrants further in deep study." (PMID 36386145, 2022). "However, the role of DOCK8 in cancer cells remains undefined." (PMID 25428919, 2015). "Numerous other genes such as ESPL1, DOCK8, ARID3A, PFKFB4, ANKZF1, BANP and GRB7 showed elevated expression rates, some of which are known or suspected to be involved in cancer development and/or progression." (PMID 37193047, 2022). "Importantly, DOCK8 deficiency affects the survival of immune cells such as T cells and NKT cells in cancer which might be through cytoskeleton reconstruction, CD4+ T cell differentiation, immune synaptic formation, tumor immune infiltration and tumor immune surveillance." (PMID 36386145, 2022).
cancer (continued). "This was confirmed by our analysis since all candidate CNVs that we have identified and that were found to affect the cancer genes PMS2, APC2, POU5F1, KANSL1, DOCK8 and TMTC3 are part of this category." (PMID 33503040, 2021). "Consequently, we recommend a spotlight on chromosome 9 aberrations affecting DOCK8 and KANK1 in NB, and especially on the sometimes denigrated FSCAs, as they could involve invasion in MNA HR-NB, as occurs in other malignant tumors." (PMID 33109237, 2020). "The qPCR results showed that KDM6A did not affect the DOCK5 and DOCK8 levels in T24 cells, indicating that KDM6A regulates Rac1 activity in a cancer type-dependent manner." (PMID 34006303, 2021).
tumor (16 papers, 2011 to 2026). "Tumour antigens LRP2 and DOCK8, which are associated with prognosis and tumour-infiltrating antigen-presenting cells, were identified in KIRC." (PMID 36851274, 2023). "In the case of phaCin-β, 14 showed a higher prevalence in neoplasia cases flanking three genes: DOCK8 (dedicator of cytokinesis 8), FAM216B (family with sequence similarity 216 member B), and Vmn2r65 (vomeronasal 2, receptor 65)." (PMID 41513643, 2026). "Based on a comprehensive analysis of the immune characteristics and prognosis of KIRC cells, LRP2 and DOCK8 are potential tumour antigens for mRNA vaccine development and are suitable for IS1–4 patients." (PMID 36851274, 2023). "In summary, DOCK8 plays an important role in the formation of immune synapses in various immune cells to enhance the killing effect of NK cells and T cells on tumor cells." (PMID 36386145, 2022). "In addition, the expression levels of LRP2 and DOCK8 were positively correlated with the abundance of tumour-infiltrating immune cells, including B cells, macrophages, and DCs." (PMID 36851274, 2023). "In summary, the role of DOCK8 on cytoskeleton reconstruction, CD4+ T cell differentiation, immune synaptic formation, tumor immune infiltration and tumor immune surveillance might be the main mechanisms for the function of DOCK8 on tumorigenesis." (PMID 36386145, 2022). "Given that DOCK8 is important for the function of NK, T cell and tumor immune surveillance, DOCK8 might play critical roles in tumorigenesis." (PMID 36386145, 2022). "DOCK8 also participates in regulating tumor cell invasion and metastatic processes." (PMID 29216821, 2017). "Of note, we further detected the gene expression levels of tumour antigens in tumour and normal tissues of 19 KIRC patients and found that the expression levels of DOCK8 and LRP2 in tumour tissues were significantly higher than normal tissues." (PMID 36851274, 2023). "Here, we summarized and discussed the critical role of DOCK8 in cytoskeleton reconstruction, CD4+ T cell differentiation, immune synaptic formation, tumor immune infiltration, tumor immune surveillance and tumorigenesis." (PMID 36386145, 2022). "In addition to this, other reports suggested that DOCK8 may have tumor suppressor functions." (PMID 33503040, 2021). "Continuing the characterization of tumor vs. non-tumor tissue, the DOCK8 gene was found to be under-expressed in HNSCC tumor samples based on Oncomine data." (PMID 38994960, 2024). "Importantly, we collected 19 KIRC samples and verified the high expression of DOCK8 and LRP2 in tumour tissues, confirming the feasibility of their development as mRNA vaccines." (PMID 36851274, 2023). "These might include genes with tumor suppressive properties, such as CDKN2B (9p21), SH3GL2 (9p22), PTPRD (9p23), and DOCK8 (9p24)." (PMID 27835607, 2016). "Moreover, qRT-PCR verified seven apoptosis-related genes (APP, DOCK8, IFI44, MDK, SLC27A2, TNFAIP2, WNT5A) with at least 2 fold changes by means of 2−ΔΔCt method, finding that APP, SLC27A2 and WNT5A had a low expression, while DOCK8, IFI44, MDK, TNFAIP2 had a high expression in ccRCC tumor tissues." (PMID 33748185, 2021). "Dedicator of cytokinesis 8 (DOCK8) can act as a tumor suppressor in non-hematopoietic tissues by directly affecting apoptosis through regulation of migration, morphology, adhesion, and growth of cells, apart from its probable role in CD8+ T cells for tumor surveillance." (PMID 34484227, 2021).